EGFR (epidermal growth factor receptor)
Diseases named in the same sentence as EGFR in open-access papers (continued):
Sharing a sentence is not in itself a finding about the gene and the disease.
melanoma (continued). "Broader gene set enrichment analysis (GSEA) of the combined transcriptomic profiles of all examined melanoma cell lines, revealed a selective enrichment of genes related to TGF-ß and EGFR signaling in those overexpressing AR or selected with BRAFi resistance." (PMID 37838724, 2023). "It is therefore possible that CL-11 induces intracellular signal transduction through homodimerization of EGFR and heterodimerization of EGFR and HER3 to mediate melanoma cell proliferation." (PMID 36883567, 2023). "Conversely, genes of the EGFR and TGF-ß pathways involved in melanoma progression and targeted drug resistance were induced by DAB treatment in AR overexpressing cells, to a much greater extent than in control cells." (PMID 37838724, 2023). "Previously, we found that ABL kinases are activated by receptor tyrosine kinases such as EGFR, PDGFR, and IGF1R, and BRAF contributes to ABL1/2 activation in melanoma cells harboring BRAF-V600E." (PMID 36765910, 2023). "It is worth mentioning that EGFR and GD2 are reported to be expressed on many other tumors beside GBM, such as melanoma and neuroblastoma, and therefore, our approach can be extended in the future to target such tumors." (PMID 37122703, 2023). "BT catechins have been found to prevent metastasis by downregulating EGFR/ERK signaling-mediated MMP expression and activity in highly metastatic melanoma models." (PMID 37305533, 2023). "In vitro analysis revealed that CL-11 can activate tyrosine kinase receptors (EGFR, HER3) and ERK, JNK, and AKT signaling pathways and has a direct stimulatory effect on murine melanoma cell proliferation." (PMID 36883567, 2023). "First, we showed that JI130 and MEL56 inhibit cell migration in two invasive melanoma cell lines (MM029 and MM165) and downregulate the mRNA expression of the main EMT/invasion markers such as AXL, EGFR, MET, ZEB1, WNT5A, TGFβ, SNAI1, TWIST and MMPs." (PMID 37508519, 2023). "EGFR, HER2, and HER3 — but not HER4 — were clearly detected by RT-PCR and WB, confirming the expression of EGFR, HER2, and HER3 receptors in B16 melanoma cells." (PMID 36883567, 2023). "For example, the expression of AXL, EGFR and NGFR, which are related to cell dedifferentiation and plasticity, is significantly higher in melanoma after drug treatment." (PMID 37483492, 2023). "EGFR, along with SOX9, are upregulated in melanoma cells with undifferentiated phenotypes, and their expressions are induced by the loss of SOX10." (PMID 35406721, 2022). "In another study, anticancer effects of RA in A375 cells melanoma cells via downregulation of ADAM17 and expression of ADAM17/EGFR/AKT/GSK3β were also evaluated." (PMID 36247004, 2022). "Combination therapy of BRAF V600E inhibitor with MEK or EGFR inhibitors enhances the efficacy compared to monotherapy and prolongs the overall survival of CRC and melanoma patients 55-58." (PMID 35966590, 2022). "Remarkably, DSF-102 was ineffective against human melanoma cells (IC50 > 100 μM), whereas it showed a prominent in vitro antiproliferative activity against human EGFR-overexpressing cells." (PMID 35954311, 2022). "While the EGFR, PROM2 mRNA in melanoma tissue was lowly expressed than that in adjacent normal tissues." (PMID 35692844, 2022). "Treatment of A375 melanoma cells with 3, 5 DCPBC for 4 and 18 h profoundly suppressed phosphorylation of critical targets like EGFR, SRC, STAT3, JNK1/2, and MSK." (PMID 35208960, 2022). "High EGFR promotes RAFi resistance in CRC, lung, melanoma and thyroid cancer cells by rapid feedback activation of EGFR signaling 113-117, and determines the G12Ci refractory state in KRAS G12C cancers 33, 34, 118-120." (PMID 35966590, 2022). "In YAP1-activated melanoma cells, SLC35B2 knockout abrogated HS surface expression and limited activity of YAP1-stimulated RTKs including ERBB3, EGFR, and AXL." (PMID 35798875, 2022).
melanoma (continued). "BRAF-mutant melanoma cells with increased expression of EGFR are less sensitive to BRAF inhibitors and elevated expression of EGFR together with NGFR characterizes pre-resistant melanoma cells, which are selected during therapy and lead to treatment failure." (PMID 35565444, 2022). "The CE-IVD labels for Idylla molecular assay are assigned only to specific tumor types for each assay-NSCLC for EGFR; CRC for KRAS, NRAS-BRAF and MSI, and melanoma for BRAF." (PMID 36293374, 2022). "NGS testing detected key driver alterations at expected prevalence rates: lung EGFR (16%), ALK (3%), RET (1%), melanoma BRAF (43%), colorectal RAS/RAF (67%), among others." (PMID 35323313, 2022). "The phenotype switching in melanoma is marked with downregulation of MITF and upregulation of RTKs, such as AXL and EGFR." (PMID 35406721, 2022). "RA possesses an inhibitory effect on melanoma cells’ proliferation, movement, and invasion via inhibiting expression of the ADAM17/EGFR/AKT/GSK3β axis." (PMID 36247004, 2022). "The results indicated that high expression of PROM2, EGFR, AURKA, and low expression of IFNG, ARNTL, FBXW7 correlated with a poor prognosis of melanoma patients." (PMID 35692844, 2022). "Among them, two compounds showed stronger inhibitory activities against both EGFR and VEGFR-2, and induced in vitro antiproliferative effect in human and murine melanoma cells, as well as in vivo antitumor activity in melanoma xenograft models." (PMID 33964953, 2021). "Collectively, our study revealed that structural hybridization strategies yielded novel and potential c-MET/EGFR/PI3K/mTOR multi-target compounds, NSC777205 and NSC777205, with promising prospects for treating melanoma, renal, CNS, colon, and NSCLC cell lines." (PMID 34512327, 2021). "In melanoma patients, the survival benefit from LRIG1 depends on EGFR levels and is lost in BRAF and RAS mutant subtypes." (PMID 33947959, 2021). "IL-24 exhibits its anti-tumor activity in a broad spectrum of cancers including melanoma through inhibition of PI3K, EGFR, and PKR induction in breast and NSCLC." (PMID 33918490, 2021). "On the other hand EGFR, galectin-3 and OPN potentially influence the extracellular signal-regulated RAF/MEK/ERK pathway [59, –, 62], and both pathways are fundamental in melanoma tumorigenesis." (PMID 34257527, 2021). "Epidermal growth factor receptor (EGFR) is a member of the RTK family and is only expressed in a subgroup of melanomas with poor prognosis." (PMID 33916908, 2021). "Negative regulation of EGFR by LRIG1 has been reported in glioblastoma multiforme and in melanoma upon hypoxia." (PMID 33947959, 2021). "It was shown that EGFR signaling regulates both invadopodia formation and ECM degradation, and that EGFR inhibitors impaired MMP expression in melanoma cells." (PMID 34360915, 2021). "In a recent RNA sequencing experiment of UACC-62 melanoma cells treated with control or NFE2L2-specific siRNA, we observed that EGFR belongs to the top 10 genes with the strongest suppression under conditions of NRF2 depletion." (PMID 33916908, 2021). "It has been shown that YTHDF2 targets a plethora of mRNAs for degradation in cancers, such as, TNFR2, c-Myc and CEBPA in leukemia, EGFR, IL11, SERPINE2 and SOCS2 in liver cancer, and PD-1, CXCR4, and SOX10 in melanoma." (PMID 33658012, 2021). "The human melanoma A375 cells were exposed to RA, then cell viability, migration, invasion, apoptosis, melanin content and the expression of ADAM17/EGFR/AKT/GSK3β were evaluated." (PMID 34224305, 2021). "To further explore the role of EGFR signaling as a target of ALOC-EO, we generated EGFR overexpressing melanoma cells (EGFR OE)." (PMID 34360915, 2021).
melanoma (continued). "In summary, our study demonstrates that ALOC-EO blocks EGFR and ERK1/2 signaling, with preclinical efficacy as a monotherapy or in combination with myelosuppressive drugs in melanoma." (PMID 34360915, 2021). "Mechanistically, ALOC-EO inhibited EGFR signaling and prevented ligand (HB-EGF)-mediated melanoma cell proliferation." (PMID 34360915, 2021). "Hyperactivation by genomic mutations in oncogenic growth-signaling molecules, such as MAPK, PI3K, and the epidermal growth factor receptor (EGFR), can also enhance CD274 expression in malignant melanoma, NSCLC, and gallbladder cancer." (PMID 34572136, 2021). "In metastasized melanoma patients, LRIG1 expression in metastases predicts survival when EGFR levels are high and in the triple wild-type subtype." (PMID 33947959, 2021). "That suggests that combination of EGFR and BRAF inhibitor shows synergistic effects in BRAF-mutant human melanoma in preclinical model." (PMID 34809598, 2021). "In contrast, regulation of EGFR and TGFA occurs by an indirect mechanism, which is enabled by the ability of NRF2 to block the activity of the melanocytic lineage factor MITF in melanoma." (PMID 33916908, 2021). "The expression of SOX10, which is a negative regulator of EGFR expression, can be decreased in BRAF mutant melanoma cells, leading to enhanced EGFR signalling upon the inhibition of BRAFV600E." (PMID 34066022, 2021). "c-MET/EGFR/PI3K/mTOR are therapeutic targets for NSC777205 and NSC777207 with consequent selective cytotoxic preferences for melanoma, renal, CNS, colon, and NSCLC cell lines." (PMID 34512327, 2021). "Receptor tyrosine kinases (RTKs) like the epidermal growth factor receptor (EGFR) and its family members ERBB2‐4 (HER2‐4) are crucial players during NMSC as well as melanoma development." (PMID 33786987, 2021). "Quinazoline and thiourea-containing sorafenib analogs have been developed as dual EGFR and VEGFR-2 TKIs and have demonstrated promising anti-tumor activity in melanoma xenografts." (PMID 33807778, 2021). "In melanoma, activation of TGF-β signaling directly upregulates the expression of EGFR and platelet-derived growth factor receptor-β, which leads to BRAF inhibitor resistance." (PMID 34247571, 2021). "RA also down-regulated the expression level of ADAM17, EGFR, p-AKT and p-GSK3β in melanoma cells, suggesting that RA had the anti-cancer potential for melanoma treatment, and the underlying mechanism may be related to inhibiting the activation of ADAM17/EGFR/AKT/GSK3β axis." (PMID 34224305, 2021). "For melanoma cells G-361, the synergistic use of CAP and silymarin nanoemulsion (SN) triggers autophagy by activating PI3K/mTOR and epidermal growth factor receptor (EGFR) pathways." (PMID 34572443, 2021). "Remarkably, signaling pathways associated with regulating the pluripotency of stem cells, cell cycle, apoptosis, focal adhesion including PI3K-Akt, Rap1, EGFR, Ras, MAPK, and proteoglycans in cancer were enriched, as well as melanoma and bladder cancer." (PMID 34070901, 2021). "In particular, we have previously demonstrated that melanoma cells treated with BRAF inhibitors upregulate the cell surface receptor Neuropilin-1 (NRP1), which elicits an EGFR-dependent mechanism of adaptive resistance to therapy." (PMID 32784465, 2020). "We focused our attention on EGFR, BRAF, KRAS, and BRAF genes for NSCLC, melanoma, and mCRC samples, respectively." (PMID 32054005, 2020). "Suppression of MITF was also associated with increased expression of ligands synergizing with EGFR activation, and autocrine EGF-EGFR circuit was observed in the cultures of resistant melanoma cell lines." (PMID 31936151, 2020). "In addition, the comparison of melanocytes with metastatic melanoma cells revealed a predominant expression of genes associated with interferon response and signaling via E-cadherin (CDH1) in melanocytes and genes involved in metastasis, EMT, and EGFR-signaling in melanoma." (PMID 32878000, 2020).
melanoma (continued). "In this paper we report for the first time, as far as we know, the expression of EGFR, HER2, HER3, and HER4 in canine melanomas." (PMID 31996230, 2020). "As reported in the literature, TBC1D16 as a driver of melanoma is a Rab4A GAP that is engaged in the trafficking of transferrin receptor and EGFR." (PMID 33194704, 2020). "Similar to what was observed in cell lines, miR-146a expression levels were inversely correlated with the levels of its target genes EGFR, CCL2 and BCL2L1 in melanoma metastases." (PMID 32967672, 2020). "Moreover, we ran CMap analysis to select a list of small molecule drugs for SKCM, such as EGFR inhibitor AG-490, growth factor receptor inhibitor GW-441756 and apoptosis stimulant betulinic-acid, which have shown therapeutic effect in the treatment of melanoma." (PMID 33392203, 2020). "NRP1 was previously shown to mediate EGFR upregulation, driving resistance to targeted therapies, such as those inhibiting BRAF in melanoma cells." (PMID 32784465, 2020). "The most promising candidates, which are expected to reduce cell growth and increase apoptosis in melanoma, involve targeting the combination of IRS1 and EGFR." (PMID 32667922, 2020). "Hypomethylation of TBC1D16 leads to the activation of TBC1D16 transcription in melanoma, and the short isoform of TBC1D16 (TBC1D16-47KDa) promotes melanoma growth and metastasis through interacting with RAB5C and regulating EGFR signaling." (PMID 33194704, 2020). "Amplification of the ERBB genes and polysomy of chromosome 7—where the EGFR gene is located—are correlated with poorer prognosis in human melanoma." (PMID 31996230, 2020). "There are other drugs that simultaneously inhibit both EGFR and HER2 (e.g., erlotinib or peletinib) and are more efficient in melanoma cell lines." (PMID 32667922, 2020). "Decorin, a major dermatan sulfate proteoglycan (DSPG), was demonstrated to regulate epidermal growth factor receptor (EGFR) signaling, thus controlling proliferation in melanoma." (PMID 32961706, 2020). "In complementary experiments, both A375 and SK-MEL-28 parental melanoma cells transfected to express exogenous Gal-1 also attained consistent NRP1 and EGFR upregulation." (PMID 32784465, 2020). "A specific protein profile was discovered for each cell line, e.g., EGFR in OSCC, Muc5AC in PDAC, and FN1 in melanoma vesicles." (PMID 32886718, 2020). "Therefore, we speculated that EGFR may be a candidate gene in pathways in cancer of melanoma." (PMID 33178610, 2020). "In preclinical testing HuMax-AXL-ADC has shown efficacy against EGFR-inhibitor-resistant NSCLC, as well as melanoma, including multidrug-resistant melanoma." (PMID 32148495, 2020). "Also, a previous preclinical study suggests that EGFR inhibitors may have different effects on melanoma cells depending on their mutational status, and that EGFR TKI-s especially in combination could be an effective approach to eliminate BRAF-mutant melanoma." (PMID 31514305, 2019). "Due to the involvement of EGFR and MET in melanoma progression, these receptors can be promising therapeutic targets." (PMID 31649529, 2019). "Regarding apoptotic escaping and cell survival, melanoma cells collected from acidic, transient and chronic, clones show a clear reduction of cleaved PARP1 and an enhanced expression of EGFR." (PMID 31275384, 2019). "FGFR3 promotes melanoma growth, metastasis, and EMT behaviors, likely by affecting the phosphorylation levels of ERK, AKT, and EGFR." (PMID 31619201, 2019). "Obtained data indicate that both EGFR and MET signalling is strictly connected with migration and invasion abilities of melanoma cells, mostly because of the regulation of their proteolytic activity and the ability to form invadopodia." (PMID 31638339, 2019). "The expression of AXL, EGFR and NGFR in melanoma has also been reported as markers for epithelial-mesenchymal transition and dedifferentiation indicating a loss of the original phenotype." (PMID 30850015, 2019).
melanoma (continued). "Our results for the first time indicate that combination of EGFR and MET inhibitors decrease melanoma cell migration and invasion." (PMID 31649529, 2019). "Previously, we demonstrated that pairs of inhibitors directed against EGFR (epidermal growth factor receptor) and MET (hepatocyte growth factor receptor) trigger a synergistic cytotoxic effect in human melanoma cells, and decrease their invasive abilities." (PMID 31877948, 2019). "In summary, our research presents the direct effect of EGFR and MET receptors protein level on the invasive abilities of melanoma cells." (PMID 31638339, 2019). "To clarify the mechanism underlying the roles of LRIG1 in hypoxia-induced aggressive potential of melanoma cells, we explored the effects of LRIG1 on EGFR/ERK signaling." (PMID 30487162, 2019). "AREG is a member of the epidermal growth factor (EGF) family and signals through epidermal growth factor receptor (EGFR), notably found on muscle cells and tumor cells including colon, breast, prostate, pancreatic, bladder, ovarian, and melanoma." (PMID 31681327, 2019). "Together, these results indicate that FGFR3 facilitates the metastasis of melanoma through ERK, AKT, and EGFR-activated EMT pathways." (PMID 31619201, 2019). "Analyzing murine B16 melanoma tumor tissues, we found a positive correlation between hypoxia, measured by HIF-1α accumulation, and EGFR levels." (PMID 31717697, 2019). "As we have previously shown, EGFR and MET seem to be promising targets for anti-melanoma combination therapy using small molecule inhibitors." (PMID 31877948, 2019). "Above‐mentioned data indicate that both—EGFR and MET signalling is directly connected with melanoma cells invasion, what establishes these receptors as promising targets for anti‐cancer treatment." (PMID 31638339, 2019). "Previously, we have also showed that pairs of inhibitors directed against EGFR (gefitinib, lapatinib), and MET (foretinib) are able to effectively decrease viability and proliferation, and induce apoptosis in examined melanoma cells." (PMID 31649529, 2019). "FGFR3 regulates malignant melanoma growth, metastasis, and EMT behaviors by influencing the phosphorylation levels of ERK, AKT, and EGFR." (PMID 31619201, 2019). "Our previous results showed that combination therapy, composed of EGFR (gefitinib or lapatinib) and MET (foretinib) inhibitors, was much more effective against melanoma cells in a comparison to a monotherapy." (PMID 31649529, 2019). "For this reason, we decided to study the effect of an EGFR (lapatinib, gefitinib) and MET (foretinib) inhibitor combination on the viability and proliferation of selected melanoma cell lines." (PMID 29719603, 2018). "Some examples of such targeted approach include erlotinib as EGFR-inhibitor for EGFR-mutant lung tumors, and vemurafenib for BRAF-mutant melanoma." (PMID 30524974, 2018). "Paraffin-embedded nuclei from 262 melanoma tissue sections were assessed for amplification in all five candidate genes (MITF, EGFR, CCND1, cMET, and cKIT)." (PMID 29492214, 2018). "Suppression of SOX10 in a proportion of melanomas can lead to TGF-β signaling and consequently to EGFR and platelet-derived growth factor receptor-β (PDGFRB) upregulation, conferring oncogene-induced senescence." (PMID 29100459, 2017). "The activity of PI3K-AKT-mTOR pathway was also shown to be upregulated as a result of the overexpression or hyperactivation of RTKs such as c-Met, EGFR and IGF1R in melanoma cells." (PMID 28708099, 2017). "Here we show that melanoma tumor growth is inhibited by 60% over controls when treated with lapatinib, a clinically approved inhibitor of ERBB2/EGFR." (PMID 28060735, 2017). "Finally and also consistent with our data, the already mentioned study regarding the EGFR‐induced slow‐growth phenotype of BRAFV600 melanoma cells that may foster the emergence of resistance cells, compared to fast‐proliferating cells, under prolonged BRAF inhibition." (PMID 28573821, 2017).